CCND1 (cyclin D1)
Diseases named in the same sentence as CCND1 in open-access papers (continued):
Sharing a sentence is not in itself a finding about the gene and the disease.
tumor (continued). "Unsurprisingly, the expression level of cyclin D1, p21, and p27 followed the progress of tumor malignancy, although Ki-67 HSPR% reached the most significant meaning (AUC 0.913, p < 0001)." (PMID 30245762, 2018). "Tumours with cyclin D1 high expression (in 50% or more of tumour cells) reached a significant relationship with the existence of numerical aberrations (Rho = 0.48; p < 0.001)." (PMID 29785357, 2018). "Seliciclib is an inhibitor of Cdk 2, 7 and 9, which has been shown to induce tumor shrinkage as well as induce tumor apoptosis, reduced expression of Mcl-1, cyclin D1 and pRB in paired tumor biopsies obtained following around 8 days of treatment." (PMID 29789630, 2018). "By inhibiting the expression of cyclin D1, Bcl-2 antagonist of cell death (Bad), and caspase-9 by increasing their phosphorylation levels, Akt promotes the G1/S transition and prevents tumor cells from undergoing apoptosis." (PMID 29736267, 2018). "Immunohistochemical expression of ANO1, β-catenin, MMP9, snail, and E-cadherin were observed in the cytoplasmic membrane, cytoplasm, and nuclei of tumor cells and the expression of cyclin D1 was observed in the nuclei of tumor cells." (PMID 29416639, 2018). "A substantial upregulated p21 expression and downregulated phospho-FOXO3a and Cyclin D1 expression was observed in the tumor tissues of mice co-administered with AsIII and Tetra." (PMID 30123091, 2018). "Protein expression levels of Cyclin-D1 are related to the site of the tumour, depth of tumour invasion and stage of the disease.." (PMID 30138436, 2018). "Cyclin D1 is necessary for tumor maintenance, and cell-cycle regulation is an effective strategy for inhibiting tumor growth." (PMID 30584449, 2018). "We found that NEAT1 inhibition plus DDP in vivo inhibited the BCL-2/caspase-3 levels and increased the BAX expression for tumor apoptosis, and also repressed the cyclin D1/CDK4 expression for cell cycle arrest." (PMID 29654165, 2018). "This phenomenon of co-localising chr8:ZNF703/FGFR1 and chr11:CCND1 amplicons tends to be seen in ER-positive tumours, among patients diagnosed at an older age." (PMID 30252041, 2018). "The tumor expressions of cyclin D1 and of FN were found higher in poor responders, than in good responders, however, the differences between the groups were insignificant (p = 0.086, p = 0.080, respectively)." (PMID 29332262, 2018). "Aberrant FGFR expression is associated with drug resistance, increased tumor cell proliferation, and survival through activation of MAPK and cyclin D1." (PMID 30326563, 2018). "The reduced tumor volume, was accompanied by a moderate but significant decrease in the Ki67 proliferation index, as well as Cyclin D1 and D3 expression in ADI-PEG20 treated xenografts and." (PMID 30108309, 2018). "There was a significantly (p = 0.022) higher expression of Cyclin-D1 in tumours of the oral cavity (19.6%; 9/46) than in those of the larynx (4.7%; 2/43) and nose (3.2%; 1/31)." (PMID 30138436, 2018).
tumor (continued). "These stainings revealed increased expression of cyclin D1 in HNSCC patient tumor samples when compared with the control tissue." (PMID 29464035, 2018). "Moreover, relative deficiency of Ctbp2, or functional inhibition, in the early progenitor niche in crypts, may suppress Apc-deficiency associated neoplasia, as Ctbp2 is a key component of the pathway between Apc loss and neoplastic transformation, via its regulation of c-Myc and cyclin D1." (PMID 30197752, 2018). "Consistent with our findings, the effects of ROS induction and the decrease in cyclin D1 expression by ZnPP treatment have been described in other tumor cell types." (PMID 30149527, 2018). "b The tumours were analysed for proliferation (c-Myc, cyclin D1) and proapoptotic (Bax) proteins by an immunoblot assay." (PMID 30185207, 2018). "NF-κΒ upregulates proteins that promote tumor growth and proliferation, such as cyclin-D1, c-myc, MMP-9." (PMID 29467927, 2018). "Downregulation of miR-365, a tumor suppressive miRNA, increases cancer cell proliferation, therapeutic resistance, and decreases apoptosis by disinhibiting expression of Cyclin-D1, BCL-2, and PI3K, while decreasing expression of PTEN." (PMID 30546829, 2018). "In treated tumor tissues we also observed decreased protein levels of cyclin D1, CDK4 and CDK6 when compared to control tumors and the IHC staining of cyclin D1 showed reduced intensity in erufosine treated as compared to untreated tumors." (PMID 29464035, 2018). "Cyclin-D1 was significantly expressed in tumours of the oral cavity (19.6%) compared to those of the larynx (4.7%) and nose (3.2%)." (PMID 30138436, 2018). "Genetic alterations that affect proteins in chromosome 11 have also been reported, such as Cyclin D1, which has been broadly studied in tumor processes." (PMID 29372649, 2018). "On one hand, GSK3β can inhibit β-catenin and subsequent tumor progression, and its downstream targets (c-myc, cyclin D1, PPARdelta) are also reported to be involved in this process." (PMID 30275459, 2018). "Next, we detected ERRα, IDH3A, c-Myc and Cyclin D1 expression by immunostaining pathological tissue sections of xenograft tumour." (PMID 30185207, 2018). "Owing to APC and CTNNB1 mutations, β-catenin signaling is hyperactivated, and several downstream targets of β-catenin, such as c-myc, cyclin D1, and PPARdelta, have been identified as markers of tumor development." (PMID 30275459, 2018). "The tumor expressions of cyclin D1 and of FN were also higher in poor responders, than in good responders, however, the differences between the groups were insignificant." (PMID 29332262, 2018). "Because cyclin D1 is a major regulator of the G1 checkpoint progression, deregulation of cyclin D1 would lead to uncontrolled cell proliferation and tumor formation." (PMID 30534074, 2018). "Multiple studies have demonstrated the tumor-promoting interplays between RSF-1 and known oncogenes or tumor suppressors, such as cyclin D1, cyclin E1, retinoblastoma (RB) and breast cancer susceptibility gene 1 (BRCA1)." (PMID 29480799, 2018). "Based on the results of the ADC xenograft mice model, DACH1 efficiently inhibited the expression of CXCL8 and the pro-proliferative factors, such as cyclin D1 and Ki-67, which in turn significantly retarded the tumor growth." (PMID 29636079, 2018). "Immunohistochemical analyses further validated CCND1 protein overexpression in both parental metastatic NPC tumor and in PDX-Bone and PDX-LN, respectively." (PMID 30236142, 2018).
tumor (continued). "The suppression of MYCN expression increased the levels of Bax and decreased the levels of Bcl‐2 and cyclin D1 proteins in cell‐derived tumour xenografts." (PMID 29673070, 2018). "CCND1 amplification and overexpression have been reported to be frequent events in several tumours including head and neck cancers." (PMID 29785357, 2018). "Cyclin D1 is a key regulator not only promoting G1/S transition, but also regulating the process of tumor progression such as cellular migration." (PMID 29684087, 2018). "A previous study showed that cyclin D1 depletion caused DNA damage via modulation of γ-H2AX and PARP and re-sensitized tumor cells to antitumor drug." (PMID 30326563, 2018). "Consistently, the FXR expression was significantly increased in non-small cell lung cancer (NSCLC), which stimulated tumor growth through the direct transactivation of the cyclin D1 (CCND1) gene." (PMID 30013008, 2018). "Our findings indicated that S100A10 contributes to tumor cell proliferation potentially via sustenance of CCND1 levels and to angiogenesis by maintaining VEGF production to ensure blood vessel development." (PMID 30009399, 2018). "CCND1 gene amplification was detected in 17 cases (9%) and correlated significantly with high tumor grade (p = 0.038), high Ki-67 protein expression (p = 0.002), and the Luminal B subtype (p = 0.002)." (PMID 29140993, 2017). "Clinic pathological studies demonstrated that cyclin D1 overexpression correlated with tumor metastasis and poor prognosis in a series of human cancers." (PMID 29262567, 2017). "Sox2 was reported as a tumor suppressor that inhibits cell growth by either regulating cyclin D1, phosphorylated Rb, or p27 (Kip1) levels, or directly activating PTEN." (PMID 28046028, 2017). "As a result, Bim and p27 were down-regulated, whereas Cyclin D1 and Slug were increased, leading to tumor cell proliferation and metastasis." (PMID 28423564, 2017). "Because of this discrepancy in radiosensitivity between the in vitro and in vivo findings we investigated the levels of the proliferation marker Ccnd1 in whole tumor lysates by Western blot analysis." (PMID 28112237, 2017). "Glycogen Synthase Kinase-3β (GSK3β), a serine/threonine protein kinase, has been considered as a potential tumor suppressor due to its ability to phosphorylate other proteins; it also has numerous cellular targets including cyclin D1 and β-catenin." (PMID 29216929, 2017). "Nevertheless, with these four pretreatment variables (NLR, Cyclin D1, p-21 and rs1800871) it is possible to build a predictive clinical model of tumor response." (PMID 28938543, 2017). "To evaluate the extent to which cyclin D1 regulates the tumor microenvironment, we performed an unbiased global secretome analysis of conditioned media from cyclin D1Stroma and controlStroma hTERT cell lines by analyzing biological triplicates for each group." (PMID 29137220, 2017). "Cyclin E1 (CCNE1) expression was significantly higher in all tumour types vs controls while Cyclin D1 (CCND1) gene expression was higher in all tumour types except prolactinomas and ACTH-secreting tumours when compared to control RNA." (PMID 28649092, 2017). "Our data indicated that FXR contributes to tumor growth via directly transactivating CCND1 and then promoting cell cycle progression." (PMID 28377627, 2017). "Box plots showing differential expression of LAST and CCND1 between normal (n = 41) and tumor (n = 454) samples." (PMID 29199958, 2017). "Representative tumour sections from the Jeko1 series showed an intense cytoplasmic cyclin D1 staining." (PMID 29066743, 2017). "Meanwhile, PKM2-mediated histone H3 modifications contribute to EGF-induced expression of CCND1 and c-Myc, tumor cell proliferation, cell-cycle progression, and brain tumorigenesis." (PMID 29299177, 2017). "In contrast, MMP2, MMP9, and Cyclin D1 levels were decreased in tumour tissues with downregulated CEP55 expression." (PMID 28724890, 2017).
tumor (continued). "Cyclin D1 and cyclin E are overexpressed in some tumor cells, where they induce cell cycle progression from G1 to S phase." (PMID 29296227, 2017). "Our immunohistochemistry results showed that CHRDL2 increased the expression of ki67 and cyclin D1, which were tumor proliferation markers." (PMID 28009989, 2017). "Next, we examined mRNA expression of HIF1α, EPO and Cyclin D1 in the tumor tissues from the initial 14 patients whose serum EPO dropped after tumor resections." (PMID 29137269, 2017). "In the tumor samples, we found significantly increased p21, cleaved caspase-3 and Ac-H3 levels, with decreased numbers of cells that were positive for Ki-67 and CCND1." (PMID 27852054, 2017). "Results showed that in LV-sh-XIST infected mouse tumor, CDK1 and Cyclin D1 protein levels were reduced, whereas P21 protein level was increased, compared with LV-sh-contr infected mouse tumor." (PMID 29371940, 2017). "Within the nucleus, EGFR induces the expression of iNOS, COX-2, c-Myc and cyclin D1, thus reprogramming important tumor growth parameters, including tumor cell proliferation and malignant progression." (PMID 28415726, 2017). "Our results confirmed CCND1 as important gene that can be used as a potential predictor in this tumor type." (PMID 28069005, 2017). "Since the proliferating cell nuclear antigen (PCNA) and cyclin D1 represent two biomarkers of tumor growth, we also evaluated their expression in tumor xenografts." (PMID 28212569, 2017). "Both the LAST and CCND1 expression levels are higher in most tumor tissues than in their corresponding normal tissues." (PMID 29199958, 2017). "Reduced expression of TUB3, survivin and cyclin D1 conditions tumor cells to be more responsive to DTX." (PMID 29340049, 2017). "These in vivo data confirm the crucial role of the subcellular distribution of cyclin D1 In tumour cell engraftment and invasion." (PMID 29066743, 2017). "Further studies showed that GTPBP4 acted as a tumor suppressor gene by regulating Merlin and cyclin D1 to inhibit cell proliferation." (PMID 29212203, 2017). "Clinically, high cyclin D1 levels were significantly associated with late-stage HCC, tumor venous infiltration, and ≥ 2 tumor nodules." (PMID 28415588, 2017). "Cyclin D1 is responsible for the progression from G1 to S phase and has been found to be overexpressed in several types of tumor." (PMID 28301579, 2017). "The expression of several biomarkers in pretreatment biopsies, such cyclin D1, p21, EGFR and VEGF have been associated with tumor response to nCRT." (PMID 28938543, 2017). "In summary, this study revealed that Kdm3a can promote mammary gland epithelial and tumor cell proliferation to facilitate mammary gland ductal elongation and tumor growth through upregulating cyclin D1 expression." (PMID 29156681, 2017). "We, then, investigated the expression of few downstream target genes of NM23-H1 involved in cell proliferation and tumor growth such as NF-kB, c-Myc and Cyclin D1; the synchronization of these genes regulate CDKs and p21." (PMID 29062040, 2017). "Compared to the control group, cyclin D1 staining in the tumor cells of quercetin-treated group exhibited a statistically significant decrease in intensity and the reduction on the percentage of positively stained cells." (PMID 28264020, 2017). "Our data demonstrated that Kdm3a can directly upregulate cyclin D1 expression to promote mammary gland epithelial cell and tumor cell proliferation." (PMID 29156681, 2017). "CDC73/parafibromin was initially recognized as a tumor suppressor by inhibiting cell proliferation via repression of cyclin D1 and c-myc genes." (PMID 29142233, 2017). "CCND1 amplification has been assumed to be critically involved in tumor initiation and progression by proto-oncogene activation." (PMID 29140993, 2017).
tumor (continued). "Tumor histological examination and immunohistochemistry showed an increase in tumor necrosis and reduction in intensity and percentage of the positive areas of cyclin D1 staining." (PMID 28264020, 2017). "The WNT/beta-catenin pathway induces also the transcription of genes involved in cell proliferation, cell invasiveness, nucleotide synthesis, tumor growth, and angiogenesis, such as c-Myc, cyclin D1, PDK." (PMID 28620312, 2017). "In the present study, we identified a significant increase in CXCL4, CXCL12, and Cyclin D1 expression in tumor samples from Chinese patients with sporadic MPNST." (PMID 29020982, 2017). "Nuclear accumulation of β-catenin promotes neoplastic conversion by triggering the cell cycle-regulators Cyclin D1 and D2 and Myc and, consequently, uncontrolled cell proliferation contributing to tumor progression." (PMID 28086833, 2017). "Mechanistically, overexpression of miR-200b in HCCC cells decreased the expression of cyclin D1 and Cdk2 in order to induce cell cycle arrest and was able restore their expression for the growth of tumor cells." (PMID 29084594, 2017). "The present study showed that high cyclin D1 and high p21 expression level in the pre-CRT tumor simple were associated with poor pathologic regression (Mandard poor response)." (PMID 28938543, 2017). "The finding that stromal cyclin D1 increased tumor growth is consistent with previous findings, in which cyclin D1 was shown to be a marker of senescent stroma and senescent stroma was shown to stimulate tumor growth." (PMID 29137220, 2017). "Cyclin D1 sphere-derived xenograft tumor models were employed to evaluate the therapeutic effects of a Smad inhibitor in combination with chemotherapy." (PMID 28415588, 2017). "The decrease in tumor size from miR-31 inhibition coincided with the reduction in Ki67+ and Cyclin D1+ proliferating cells, and correlated with reduced Wnt activity and increased BMP and TGFβ activities." (PMID 28870287, 2017). "In contrast, DEN/PB-induced tumor tissue derived from wild type mice exhibited a markedly increased expression of Ccnd1." (PMID 28915576, 2017). "In contrast to the behavior of cyclin A, cyclin D1, pmTOR and pRaptor, p27 was massively reduced in the temsirolimus-resistant tumor cell lines." (PMID 29299126, 2017). "Comparison of the immunohistochemistry scoring of cyclin D1 expression in HepG2 tumor tissues between the quercetin-treated and control groups (control vs quercetin, *p< 0.05)." (PMID 28264020, 2017). "c-src plays an important role in cell cycle progression in many tumor cells, and suppressing c-src downregulates cyclin D1 and cyclin E and upregulates p27 Kip1." (PMID 28141839, 2017). "MiR-373 act as a tumor suppressor role during BCa progression by recovering E-cadherin expression which leads to down-regulation of Cyclin D1, C-myc and MMP2, therefore inhibits cells proliferation, migratory and invasive capacity." (PMID 29212202, 2017). "Altogether, we found that FXR acts as a novel proto-oncogene in NSCLC via the target gene CCND1, driving cell cycle progression and tumor growth." (PMID 28377627, 2017). "In contrast, cyclin proteins, such as cyclin A, cyclin B and cyclin D1, express aberrantly in tumor species." (PMID 27974673, 2017). "IB revealed an accumulation of cyclin D1 in the cytoplasm of primary tumour cells in one (#6414) of three MCL patients tested." (PMID 29066743, 2017). "On contrary, some histopathological data do not show a statistically significant difference in the level of this cyclin, and others suggest that cyclin D1 expression significantly increases due to tumor progression yet decreases in metastases." (PMID 29214525, 2017).